BAHD1 (bromo adjacent homology domain containing 1)
Description:
Heterochromatin protein that acts as a transcription repressor and has the ability to promote the formation of large heterochromatic domains. May act by recruiting heterochromatin proteins such as CBX5 (HP1 alpha), HDAC5 and MBD1. Represses IGF2 expression by binding to its CpG-rich P3 promoter and recruiting heterochromatin proteins. At specific stages of Listeria infection, in complex with TRIM28, corepresses interferon-stimulated genes, including IFNL1, IFNL2 and IFNL3.
Synonyms: KIAA0945
Tractability: PROTAC: UniProt records ubiquitination sites on it; ubiquitination databases record sites on it.
Gene: Protein-coding gene on chromosome 15 (40,436,611 to 40,468,242, forward strand). Ensembl gene ENSG00000140320.
Subcellular location: Nucleus; Chromosome
Subcellular location (Human Protein Atlas): Nucleoplasm
Gene Ontology:
Molecular function: chromatin binding; protein binding; transcription cis-regulatory region binding
Biological process: heterochromatin formation; negative regulation of DNA-templated transcription
Cellular component: chromatin silencing complex; nucleoplasm; chromosome; nucleus
Genetic constraint (gnomAD): Loss-of-function variants: 20 observed, 64.98 expected, observed/expected ratio (o/e) 0.31, 90% interval 0.22 to 0.45. The upper end of that interval is the gene's LOEUF score, 0.45, which puts it in group 1 of 6, group 1 being the genes least tolerant of losing a copy. Missense variants: 939 observed, 1,106 expected, observed/expected ratio (o/e) 0.85, 90% interval 0.8 to 0.9. Synonymous variants: 408 observed, 440.49 expected, observed/expected ratio (o/e) 0.93, 90% interval 0.85 to 1.
Homologues: Orthologues: chimpanzee BAHD1 (100% identical), rabbit BAHD1 (94% identical), guinea pig BAHD1 (93% identical), dog BAHD1 (93% identical), pig BAHD1 (92% identical), mouse Bahd1 (91% identical), rat Bahd1 (91% identical), macaque BAHD1 (88% identical), tropical clawed frog bahd1 (46% identical), zebrafish bahd1 (35% identical), Drosophila melanogaster wge (17% identical). Paralogues in human: BAHCC1 (21% identical), TNRC18 (20% identical).
Diseases named in the same sentence as BAHD1 in open-access papers:
BAHD1 is named in the same sentence as 25 diseases in open-access papers, as found by Europe PMC text mining. Sharing a sentence is not in itself a finding about the gene and the disease. The quoted sentences say what the papers report.
Anxiety (4 papers, 2020 to 2025). Intense feelings of nervousness, tension, or panic often arise in response to interpersonal stresses. "The Bahd1 null mutation causes significant perinatal death in mice, whilst the Bahd1+/− heterozygotes exhibit anxiety‐like behaviors suggesting a potential role of BAHD1 in the rodent nervous system." (PMID 37594178, 2023). "Similarly, BAHD1 has also been suggested to regulate brain cells and, consequently, to be linked to anxiety-like behavior." (PMID 36658485, 2023). "Bahd1+/- mice showed anxiety-like behavior and reduced prepulse inhibition (PPI) of the startle response." (PMID 32407325, 2020). "Here, we show that BAHD1 haploinsufficiency in the mouse led to behavioral alterations relevant to anxiety-like and neuropsychiatric disorders." (PMID 32407325, 2020). "Different anxiety tests (i.e. the open field, novel object recognition, step-down and acoustic startle response) suggested that BAHD1 haploinsufficiency increased anxiety-related behavior." (PMID 32407325, 2020). "On the other hand, at 110 dB mice Bahd1-Het2 mutants displayed significantly higher acoustic startle responses (SAs) compared to WT mice, which could be interpreted as increased anxiety, in line with the results obtained in the open field test." (PMID 32407325, 2020). "Together, these results suggested that a decrease in Bahd1 expression could increase anxiety." (PMID 32407325, 2020). "Thus, in agreement with the results obtained with the first cohort, haploinsufficiency in Bahd1 expression does not significantly impair muscular function or motor coordination but induces anxiety-like behavior." (PMID 32407325, 2020).
listeriosis (3 papers, 2016 to 2022). A bacterial infection caused by Listeria monocytogenes. "In the case of Listeria infection of epithelial cells, BAHD1 represses the expression of genes stimulated by interferons (ISGs), particularly interferon lambda." (PMID 32244550, 2020). "The fact that BAHD1 is involved in placental function now opens the possibility that BAHD1 contributes to the fetoplacental step of listeriosis, as L. monocytogenes has a tropism for the placenta." (PMID 26938916, 2016).
behavioral disorders (1 paper, 2020). "Together, these data support the hypothesis that BAHD1 dysfunction could contribute to behavioral disorders." (PMID 32407325, 2020).
breast carcinoma (1 paper, 2016). "BAHD1-mediated regulation of ESR1 is also enticing as ESR1 is a key regulator in a variety of biological processes and ESR1 deregulation has been implicated in several diseases, including breast cancer." (PMID 26938916, 2016).
head and neck cancer (1 paper, 2024). A primary or metastatic malignant neoplasm affecting the head and neck. "Taken together, our findings support the notion that BAHD1 overexpression is implicated in the radioresistance of our prostate and head and neck cancer models through modulation of the heterochromatin response to IR." (PMID 39719436, 2024). "Taken together, our results support a new model implicating BAHD1-dependent modulation of the heterochromatin in acquired radioresistance of prostate and head and neck cancers." (PMID 39719436, 2024). "Here, we reported an upstream mechanism whereby heterochromatin formation is increased by BAHD1 overexpression in our RR prostate and head and neck cancer models." (PMID 39719436, 2024). "Herein, we have demonstrated the utility of our platform that led to the discovery of a new pathway for radioresistance involving BAHD1-dependent modification of the heterochromatin that was a dominant molecular phenotype in our RR prostate and head and neck cancer models." (PMID 39719436, 2024). "While we acknowledged that our earlier results suggest that DSB repair capacity only differed for 22Rv1, nonetheless, we uncovered an interplay between manipulation of BAHD1 expression and DSB induction and repair in both our RR prostate and head and neck cancer cells." (PMID 39719436, 2024). "We then hypothesised that the 5 upregulated genes (namely, ATPase phospholipid transporting 8A1 [ATP8A1], BAHD1, cathepsin [CTSD], janus kinase 1 [JAK1], and myosin regulatory light chain interacting protein [MYLIP]) play a role in radioresistance of prostate and head and neck cancers." (PMID 39719436, 2024).
Hypocholesterolemia (1 paper, 2016). An decreased concentration of cholesterol in the blood. "We show that disruption of the Bahd1 gene in the mouse leads to a placental growth defect associated with low birth weight and neonatal death, hypocholesterolemia and decreased body fat in surviving adults." (PMID 26938916, 2016). "Here, we demonstrate that ablation of the Bahd1 gene results in hypocholesterolemia, hypoglycemia and decreased body fat in mice." (PMID 26938916, 2016). "This functional convergence is striking and consistent with the observed hypocholesterolemia and hypolipidaemia in Bahd1-KO mice." (PMID 26938916, 2016).
Intrauterine Growth Restriction (1 paper, 2016). "More generally, a connection between BAHD1 and placenta-associated pathologies, such as Intrauterine Growth Restriction and Pre-Eclampsia, should be carefully examined." (PMID 26938916, 2016).
language delay (1 paper, 2024). "Our Qatari individual, subject 3, with ASD and language delay, carried a homozygous missense variant in this gene, while one silent and eight missense heterozygous variants reported sporadically in BAHD1 in ASD individuals were heterozygous." (PMID 39519104, 2024).
lung carcinoma (1 paper, 2007). "Next, the human lung cancer cell lines A549 and H1299, in which OLIG1, BAHD1, and DMRTA1 are methylated and not expressed, were treated with 1 μM of 5-aza-2′-deoxy-cytidine (5-aza-dC) for 48 and 72 h." (PMID 17388669, 2007).
mental disorder (1 paper, 2020). A disease that has its basis in the disruption of mental process. "Interestingly, during the course of our study, the BAHD1 human gene was identified as a disease locus correlated with mental disorder." (PMID 32407325, 2020). "By considering their phenotypes, Bahd1+/- mice may provide a novel model for human mental disorders." (PMID 32407325, 2020).
bacterial infection (3 papers, 2015 to 2023). "BAHD1 silences IFN‐stimulated genes and modulates innate immune defense in response to bacterial infection." (PMID 37594178, 2023). "Also of interest is the presence in a subset of BAHD1-DMRs of binding sites for the transcription factor SP1, with which BAHD1 co-immunoprecipitates, as well as for STAT factors that may act in synergy with BAHD1 to repress immunity gene expression during a bacterial infection." (PMID 26648976, 2015).
cancer (3 papers, 2022 to 2024). A tumor composed of atypical neoplastic, often pleomorphic cells that invade other tissues. "Finally, we posit that the BAHD1-dependent pathway influences the radiosensitivity of our cancer models by modulation of DNA repair, thereby providing a new model that is implicated in cancer radioresistance." (PMID 39719436, 2024). "Given the published literature linking the heterochromatin response to radiation effects in cancer cells, we chose to focus on elucidating the role of BAHD1 in modulating H3K27me3 and H3K9me3 expression following IR of our 22Rv1- and FaDu-RR and -WT cells." (PMID 39719436, 2024). "Our data thus suggest the mechanistic linkage between BAHD1 and the enhanced heterochromatin response in our RR cancer models." (PMID 39719436, 2024). "From these analyses, we uncovered a new heterochromatin modification pathway via BAHD1 overexpression that was a molecular driver of radioresistance in these cancers." (PMID 39719436, 2024). "To confirm the involvement of BAHD1 in modulating the expression of H3K9me3 and H3K27me3, we next performed functional knockdown experiments of BAHD1 using the siRNA approach in both cancer models." (PMID 39719436, 2024). "Further understanding of BAHD1 modification of the chromatin structure to influence radiosensitivity could help to discover therapeutic targets against this molecular vulnerability of RR cancers." (PMID 39719436, 2024). "While BAHD1 knockdown seemingly reduced the heterochromatin response and led to increased DSB induction and reduced repair in both 22Rv1-RR and FaDu-RR cells, the differences in DDR were not obvious in the baseline comparisons between the RR and WT cancer cells." (PMID 39719436, 2024).
infection (2 papers, 2016 to 2020). The state of being infected such as from the introduction of a foreign agent such as serum, vaccine, antigenic substance or organism. "We have previously identified a link between BAHD1 and interferon responses during the infection of human epithelial cells by the bacterial pathogen L. monocytogenes." (PMID 32407325, 2020). "Given the role of BAHD1 in the expression of immunity genes, it is also possible that the recurrent infections in the patient were also part of the translocation phenotype." (PMID 32407325, 2020). "We also demonstrated that infection by a bacterial pathogen triggers BAHD1-mediated repression of Interferon-Stimulated Genes (ISGs) in epithelial cells." (PMID 26938916, 2016). "We previously identified a role for BAHD1 in infection of epithelial cells with the bacterial pathogen Listeria monocytogenes." (PMID 26938916, 2016). "We have demonstrated that BAHD1 is a chromatin regulator that plays a role in the infection of epithelial cells by the bacterial pathogen Listeria monocytogenes and that modulates expression of interferon-stimulated genes (ISG) upon infection." (PMID 32407325, 2020).
tumour (2 papers, 2021 to 2025). "Based on this finding, increasing number of studies unveil the regulatory roles of BAHD1 in cell proliferation, differentiation, inflammation, development, and tumour metastasis." (PMID 41327336, 2025). "PNA-A15 treatment upregulated A-T repeat-containing genes that act as tumour suppressor genes, such as BAHD1, CCAR1, EGR1, and SLC5A11." (PMID 34059086, 2021).
brain disorder (1 paper, 2020). A disease affecting the brain or part of the brain. "It is important to emphasize that Płoskia and collaborators recently reported the first genetic alteration of the human BAHD1 gene and correlated this mutation with brain disorders." (PMID 32407325, 2020).
infectious disease (1 paper, 2020). A disorder directly resulting from the presence and activity of a microbial, viral, or parasitic agent in humans. "During our research on an infectious disease, we serendipitously identified the Bromo Adjacent Homology Domain containing 1 (BAHD1) protein as a central component of a novel complex associated with HDAC1/2." (PMID 32407325, 2020).
metabolic disease (1 paper, 2016). A congenital disorder (due to inherited enzyme abnormality) or acquired (due to failure of a metabolically important organ) disorder resulting from an abnormal metabolic process. "Our data also implicate BAHD1 in mammalian metabolic regulation and several BAHD1 candidate target genes have been associated with metabolic diseases in humans." (PMID 26938916, 2016). "Detailed understanding of how and where BAHD1 complexes establish repressive chromatin states could be instrumental for the development of new strategies for selective treatment of metabolic disorders in the future." (PMID 26938916, 2016).
psychiatric disorder (1 paper, 2020). A disorder characterized by behavioral and/or psychological abnormalities, often accompanied by physical symptoms. "Altogether, these results suggest that BAHD1 plays a role in chromatin-dependent gene regulation in a subset of brain cells and support recent evidence linking genetic alteration of BAHD1 to psychiatric disorders in a human patient." (PMID 32407325, 2020).
BAHD1 also shares sentences with these, for which no sentence is quoted: adenocarcinoma (1 paper); autism (1); colitis (1); glioblastoma (1); Hypoglycemia (1); Pre-Eclampsia (1); ulcerative colitis (1).